BRCA1 (BRCA1 DNA repair associated)
Diseases named in the same sentence as BRCA1 in open-access papers (continued):
Sharing a sentence is not in itself a finding about the gene and the disease.
breast cancer (continued). "Hence, PALB2 missense variants causing the loss of the binding with BRCA1 might confer different risk magnitude for breast cancer." (PMID 30410870, 2018). "Furthermore, phase II/III studies of single-agent PARP inhibitors (PARPi) have shown encouraging progression-free survival results in patients with BRCA1/2-mutated breast cancer, which led to the recent approval of olaparib, the first PARPi to be approved in breast cancer." (PMID 29867226, 2018). "Finally, additional screening for breast cancer and risk-reducing interventions through chemoprevention and surgical procedures can be undertaken by the individual and family members who are known BRCA1 or BRCA2 germline mutation carriers to prevent future cancers." (PMID 29506471, 2018). "However, in BRCA1 mutation carriers a younger age at first IVF treatment seemed to be more strongly related with breast cancer risk than first IVF treatment at older ages (≤32 years HR: 1.91, 95% CI: 0.88–4.16, >32 years HR: 0.70, 95% CI: 0.28–1.76), but numbers were small." (PMID 29937543, 2018). "Thus from current study it is concluded that BRCA1 185 Del AG has association with early age onset of breast cancer and exon specific selection of cohort for direct sequencing of different mutational analysis is a useful approach to be applied on BRCA analysis." (PMID 30344568, 2018). "Therefore, the loss of the ring finger domain of BRCA1 and consequently, loss of E3 ubiquitin ligase activity may be an important event in the development and progression of breast cancer." (PMID 29459887, 2018). "Our molecular characterization of BRCA1-deficient lacrimal acinic cell carcinoma using immunohistochemistry showed that proliferating acinic cells overlapped with the expression of cyclin D1, revealing a property in common with BRCA1-associated mammary tumors in mice." (PMID 30652068, 2018). "However, we also observed functional mutations to BRCA1 in breast cancer." (PMID 29485617, 2018). "In addition to tamoxifen therapy, shared BRCA1/2 gene mutations may contribute to a higher risk of corpus uteri cancer among breast cancer patients, compared to the general population." (PMID 29556910, 2018). "Finally, PARP inhibition could be advantageously associated with emerging immune checkpoint inhibitors in BRCA1/2-mutated breast cancers, based on several observations." (PMID 30544963, 2018). "While increased glucose and other nutrients might alter the ability of BRCA1 to function as a tumor suppressor, pre-pubertal estrogen exposure could increase the ability of major breast cancer susceptibility genes to prevent breast cancer through cellular differentiation." (PMID 30390716, 2018). "The cumulative lifetime risk of developing breast cancer associated with a BRCA1 or BRCA2 mutation, up to age 80, may be as high as 72% and 69%, respectively, and approximately 5–10% of newly diagnosed breast cancers are thought to be attributable to a BRCA1 or BRCA2 mutation." (PMID 29752676, 2018). "However, an earlier study from the same country that included 72 unrelated patients with positive family history of breast and/or ovarian cancers or with an early onset breast cancer reported higher carrier rates; deleterious BRCA1 and BRCA2 mutations were reported in 12.5%." (PMID 29409476, 2018). "The prevalence of germ line mutations in non‐BRCA1/2 genes associated with hereditary breast cancer (BC) is low, and the role of some of these genes in BC predisposition and pathogenesis is conflicting." (PMID 29522266, 2018).
breast cancer (continued). "Moreover, several studies showed that high rate and long history of consanguinity, commonly observed in developing countries, decrease breast cancer incidence rate by decreasing the frequency of mutations in high penetrant breast cancer genes such as BRCA1 and BRCA2." (PMID 30594178, 2018). "However, the Canadian study included breast cancer patients with the BRCA1 mutation." (PMID 30586919, 2018). "Furthermore, R-loops accumulate in human cells depleted of DNA repair factors that act during replication, such as those involved in the FA/BRCA pathway, that is in the tumor suppressor and breast cancer-susceptibility genes BRCA1 and BRCA2 or the Fanconi anemia (FA) factors FANCD2, FANCA or FANCM." (PMID 28653981, 2017). "MYC overexpression correlated with poor prognosis in sporadic breast cancer with susceptibility gene 1 (BRCA1) deficiency with a TNBC phenotype, and thus, a combination therapy targeting BRCA1 deficiency and the MYC pathway may provide a promising strategy for this specific subtype of breast cancer." (PMID 28696357, 2017). "Comprehensive studies on the pathology of hereditary breast cancer is needed to characterize variants of uncertain clinical significance (VUS) increasingly uncovered by WES, which may use lower thresholds for breast cancer mutation screening compared to targeted BRCA1/2 mutation screening." (PMID 28241424, 2017). "The results from both settings support the association between low nuclear BRCA1 detection and poor prognostic indicators such as older age, higher tumor grades, weak ER and Her2 expression, and high proliferation index as well as positive family history of breast cancer." (PMID 28863181, 2017). "Our study suggests that one BRCA1 variant may be associated with increased risk of breast cancer." (PMID 28222693, 2017). "One possible explanation for the observed interaction between age and the ER-negative breast cancer PRS in BRCA1 mutation carriers could due to the use of the ER-negative breast cancer PRS from the general population to predict the risk of overall breast cancer risk for BRCA1 mutation carriers." (PMID 28376175, 2017). "The All Breast Cancer in Malmö (ABiM) study, a well-characterized, population-based, prospectively collected cohort of 273 breast cancer patients, diagnosed during the period of 2007–2009 at a single institution, was retrospectively analyzed for the presence of germline BRCA1 and BRCA2 mutations." (PMID 28120249, 2017). "In addition, novel data show that RANKL signaling could be important in BRCA1 mutation-driven mammary cancer, and RANKL inhibition in breast organoids derived from pre-neoplastic BRCA mutation tissue attenuated progesterone-induced proliferation." (PMID 29088745, 2017). "Furthermore, several studies have postulated that pre-pubertal estrogenic exposure may reduce adult breast cancer risk by inducing persistent upregulation of a tumor suppressor gene (BRCA1) in the mammary gland." (PMID 28732505, 2017). "Breast cancer (BC) is the leading cancer among women worldwide and is of hereditary origin in 5–10% of cases, mainly due to BRCA1/2 mutations." (PMID 28542378, 2017). "Hence, in women with a newly diagnosed breast cancer, knowledge of BRCA1/2 mutation may impact the surgical choices in favor of bilateral mastectomy." (PMID 28770017, 2017). "However, other work has shown that PKM2 is dispensable for the growth and maintenance of xenograft tumors, that loss of PKM2 can promote progression of BRCA1 loss-driven breast cancer and medulloblastoma tumor growth, and that PKM2 is not required for leukemia or liver tumor formation." (PMID 29214019, 2017). "SNP1 (rs4986850) was located in the BRCA1 gene and may confer increased risk for breast cancer." (PMID 28612167, 2017).
breast cancer (continued). "Whilst the low level of detection of BRCA1 and BRCA2 mutations amongst individuals with HER2+ breast cancers is clearly important in assessing carrier likelihood, the presence of a triple negative breast cancer clearly increases the likelihood of identifying a BRCA1/2 mutation." (PMID 27796713, 2017). "Thus, in addition to being a marker of basal-like features, Nestin might have predictive value in testing breast cancer patients for BRCA1 germline mutations, although details concerning analytical and clinical validity should be further studied." (PMID 28439082, 2017). "Moreover, BRCA1 methylation is also associated with poor survival in breast cancer patients." (PMID 29152070, 2017). "As VDR, RXR and PPARγ can be quantified in cancer tissue easily, they - given them being present in BRCA1 mutated breast cancer cases at all - may evolve as novel alternative biomarkers, especially for hormone receptor negative or even triple negative breast cancer patients." (PMID 28427429, 2017). "Therefore, mutated BRCA1 or BRCA2 is a main genetic determinant of breast cancer occurrence." (PMID 29469819, 2017). "Although the mutation status of Rak and BRCA1 is unknown, we found that there is a positive correlation between Rak and BRCA1 expression (Pearson’s r = 0.707759, p < 0.05), suggesting a potential link between Rak and BRCA1 expression in breast cancer." (PMID 29156836, 2017). "Indeed, the human HCC1937 breast cancer cell line, harbouring a BRCA1 deletion as well as a hypomorphic BRCA1 allele with a 5382insC frameshift mutation, showed increased chromatin bridges in anaphase and telophase upon olaparib treatment, as well as lagging chromosomes." (PMID 28714471, 2017). "To test this hypothesis, we applied cell survival assays, immunofluorescence staining, DNA fiber and western blot analyses to look at the correlation between cell survival and genome integrity in control, EEPD1, RAD52 and EEPD1/RAD52 co-depletion BRCA1-deficient breast cancer cells." (PMID 29145865, 2017). "Indeed, mutations in the BRCA1 gene are responsible for approximately 40% of inherited breast cancer and specific mutations such as the BRCA1 5382insC mutation increase by 10 times the risk of getting breast cancer." (PMID 28858236, 2017). "It is estimated that known breast cancer susceptibility loci including BRCA1 and BRCA2 account for approximately 20% of familial risk, with the remaining variation caused by mutations with low-moderate penetrance that may be inherited in a subtype specific manner." (PMID 28241424, 2017). "Thus, RANKL inhibition using an approved drug might be a feasible strategy to, for the first time, prevent breast cancer in BRCA1-mutation carriers and possibly in other women at high risk for developing breast cancer." (PMID 27881737, 2016). "Importantly, for the development of new strategies to prevent the onset of BRCA1-related breast cancer, this study suggests that a subset of women with BRCA1 mutations could be candidates for a UPA treatment as a preventive breast cancer strategy." (PMID 27246982, 2016). "Besides preventive measures that are available for patients who test positive for a BRCA1/2 gene mutation and have increased risk to develop a second primary breast cancer and ovarian cancer, GCT also provides information for the family members of tested individuals." (PMID 26833044, 2016). "Previous studies have provided some evidence, in known breast cancer susceptibility genes BRCA1 and BRCA2, of genetic variants associated with allelic expression differences which could affect the risk of breast cancer in mutation carriers through altering expression levels of the wild-type allele." (PMID 27792995, 2016).
breast cancer (continued). "Moreover, NEAT1 is crucial for tumorigenicity of BRCA1-deficient breast cancer." (PMID 27556296, 2016). "The vast majority of cancers arise spontaneously hence their prediction is impossible although certain populations may benefit such as those predisposed to certain cancers e.g. women who carry the defective BRCA1 or BRCA2 genes which predispose to breast cancer." (PMID 27412241, 2016). "Although protein abundance and mRNA expression may not consistently correlate because of e.g. post transcriptional regulation, our findings suggest that proteins highly released by BRCA1-deficient breast cancer cell line, when mapped to mRNA transcript, may enrich BRCA1/2-related breast cancer." (PMID 27566577, 2016). "Furthermore, the G allele of rs1801123 was associated with an increased risk of breast cancer in women carrying the BRCA1 mutation, although in a recent study of the same group using a large set of BRCA1 and BRCA2 mutation carriers, its lack of association was revealed." (PMID 27483248, 2016). "Several studies have shown that exposure to diagnostic X-rays may cause cancer in healthy BRCA1 mutation carriers, whereas researchers in other studies could not detect a positive association between exposure to IR and breast cancer risk in BRCA1/2 mutation carriers." (PMID 27184744, 2016). "Compared to white (W) women, black (B) women with breast cancer are more likely to be younger at diagnosis, carry hormone receptor (HR)-negative breast cancer, present with more advanced stage at diagnosis, and have higher rates of BRCA1/2 mutations or polymorphisms." (PMID 26759753, 2016). "Of them, 11 was irrelevant to 1298A>C polymorphism, four focused on breast cancer mortality, one conducted among the same patients and controls with another study, but provided less completed data, and for one study, the controls were chosen from BRCA1 carriers." (PMID 27568010, 2016). "Given that both ER− and ER+ BRCA1 breast cancers seem to originate from a common luminal progenitor cell population, it has been suggested that ER status of breast cancer occurring in BRCA1 mutation carriers may be under control of different molecular mechanisms." (PMID 26857456, 2016). "In addition, the expression levels of FOXO3 and FOXA1 may also be useful biomarkers to molecularly classify BRCA1-mutated breast cancers." (PMID 27043660, 2016). "The prevalence of pathogenic BRCA2 mutations in breast cancer cases is, however, less than for BRCA1 in most of Western Europe and North America, which may be why reports on the outcome of early diagnosis with MRI in carriers of pathogenic BRCA2 mutations are even sparser." (PMID 27087880, 2016). "Maternal exposure to AhR agonists has been proposed as a risk factor for breast cancer in the offspring through epigenetic inhibition of the tumor suppressor BRCA-1 (Breast cancer 1), whereas dietary AhR antagonists may exert protective effects against such disease." (PMID 27243009, 2016). "The variant causes the loss of a canonic donor splice site at position +2 in BRCA1 intron 21; and consequently the partial retention of 156 bp of intron 21 in the patient’s transcript; which demonstrates that this novel BRCA1 mutation plays a pathogenetic role in breast cancer." (PMID 28009814, 2016). "This association was independent of the presence of TNBC and age suggesting that assessment of TOP1 may substantially improve prediction of BRCA1/2 mutations, in particular in breast carcinomas with hormone-receptor positive or HER2 positive breast cancer diagnosed in women aged ≥ 45 years." (PMID 27566577, 2016).
breast cancer (continued). "The results reported here indicate that both phosphorylation of eIF2α and levels of BRCA1 may provide needed biomarkers for future clinical studies assessing the potential effect of n-3 PUFAs on breast cancer risk and perhaps identifying individuals that may benefit from dietary intervention." (PMID 25762631, 2015). "The pooled breast cancer-specific survival estimates were a 10-year absolute worse difference of 6.8% and a HR of 1.12 (95% CI 0.71–1.53); in contrast, the adjusted HR showed a slightly better breast cancer-specific survival for BRCA1 mutation carriers (0.92, 95% CI 0.58–1.36)." (PMID 25816289, 2015). "Also, the reduction in BRCA-1 expression observed in peritumoral tissue suggested that Brca-1 CpG methylation may be an epigenetic event that occurs prior to overt mammary tumor formation linked to Ahr overexpression and/or activation." (PMID 26715507, 2015). "Therefore, we performed an updated meta-analysis to aim to come up with the highest level of evidence for the associations between three SNPs in TOX3 gene and breast cancer risk among diverse ancestry populations and distinct tumor subtypes stratified by estrogen receptor (ER) or BRCA1/BRCA2." (PMID 26239137, 2015). "Therefore, understanding if changes in expression and/or activation of the AhR are associated with somatic inactivation of the BRCA-1 gene may provide clues for breast cancer therapy." (PMID 26715507, 2015). "Indeed, as breast cancer appears before GBM in BRCA1 mutated patients, increased survival because of improved treatments may now allow the recording of brain tumour development." (PMID 25880076, 2015). "Based on these results we can conclude that clinico-pathological characteristics of the tumour might indeed play a confounding or mediating role in the association between BRCA1/2 mutation carriership and breast cancer survival, though more research should be performed to further elucidate this." (PMID 25816289, 2015). "Finally, the detection of a germline mutation in 1 of 450 high-risk breast cancer patients with normal BRCA1/2 suggests that UBE2T also could be a very rare cancer susceptibility gene." (PMID 26085575, 2015). "Thus, the possibility of resistance to IR treatment may have to be considered when breast cancer patients with a deficiency in both BRCA1 and 53BP1 are treated with IR in the clinic." (PMID 25586219, 2015). "In addition, BRCA1 mutated and sporadic breast cancers differed regarding patient age (p < 0.001)." (PMID 26029931, 2015). "However, the apparent enrichment of BRCA1/BRCA2 mutation carriers among ovarian cancer cases with a prior or coincident invasive breast cancer would advocate genetic testing of ovarian cancer cases with breast cancer in the French Canadian population." (PMID 25884701, 2015). "In women with BRCA1 germline mutation, the incidence of “sporadic” breast cancer, with an oncogenesis independent from BRCA loss of function, is unknown but this case proves that such tumors do exist and must be taken into account when developing targeted therapies." (PMID 26426992, 2015). "Furthermore our findings are in keeping with a previous study which examined the association of tissue composition with mammographic density in high breast cancer risk patients undergoing risk-reducing mastectomy, including nine BRCA1 and BRCA2 mutation carriers." (PMID 26110820, 2015). "In addition to the main effects, interaction between HMMR and AURKA, and between HMMR and TUBG1 could influence breast cancer risk in BRCA1 and BRCA2 mutation carriers." (PMID 25830658, 2015).